KIF11 (kinesin family member 11)
Diseases named in the same sentence as KIF11 in open-access papers (continued):
Sharing a sentence is not in itself a finding about the gene and the disease.
triple-negative breast carcinoma (3 papers, 2017 to 2021). An invasive breast carcinoma which is negative for expression of estrogen receptor (ER), progesterone receptor (PR), and human epidermal growth factor receptor 2 (HER2). "In conclusion, our study provides extensive evidence to demonstrate that KIF11 inhibitor 4bt showed pronounced antitumor activity, acting in key points of tumorigenesis and cancer progression in in vivo xenograft model of triple negative breast cancer." (PMID 34548908, 2021). "Our data provide extensive evidence to demonstrate that KIF11 inhibitors showed pronounced antitumor activity, acting in key points of tumorigenesis and cancer progression in in vivo xenograft model of triple negative breast cancer, like down-regulation of KIF11 and ALDH1-A1." (PMID 34548908, 2021).
autosomal recessive primary microcephaly (2 papers, 2015 to 2016). Autosomal recessive primary microcephaly (MCPH) is a rare genetically heterogeneous disorder of neurogenic brain development characterized by reduced head circumference at birth with no gross anomalies of brain architecture and variable degrees of intellectual impairment. "To date, 16 loci and genes have been associated with autosomal recessive primary microcephaly (MCPH), and two genes, KIF11 and DYRK1A, have been linked to autosomal dominant primary microcephaly." (PMID 27008544, 2016).
COVID-19 (2 papers, 2023 to 2024). A disease caused by infection with severe acute respiratory syndrome coronavirus 2. "CDC20 and KIF11 were listed as hub genes for COVID-19 treatment and novel therapeutic targets against SARS-CoV-2 infections." (PMID 36911196, 2023). "TPX2 and KIF11 were upregulated in peripheral blood mononuclear cells and contributed to diagnosing and managing COVID-19 patients." (PMID 36911196, 2023). "Additionally, in a study published in 2021, a correlation was also found between Eg5 and COVID-19: KIF11 is among the key genes altered in blood cells from patients infected, compared to normal blood cells." (PMID 38939361, 2024). "In the study of tissue regeneration after acute injury, we analyzed the database of ALF and COVID-19 by bioinformatics method and found common hub genes, including CDC20, CENPF, KIF4, KIF11, NUSAP1, TPX2, and PTTG1, which were related to mitosis and cell cycle regulation." (PMID 36911196, 2023).
diabetes (2 papers, 2013 to 2024). "Four single nucleotide polymorphisms (SNPs) of the KIF11 gene identified in the GWAS catalogue are associated with diabetes, including RS2153827, RS6583826, and RS7087591, which are all associated with the risk of T2DM, while RS7096101 is associated with insulin level." (PMID 38915894, 2024). "In these studies, we have identified multiple genes, including CAMK1D, CDKAL1, TSPAN8 and KIF11, whose implied role in diabetes from the GWA studies was further supported by effects seen on gluconeogenic and glyconeogenic pathways in primary human hepatocyte cultures." (PMID 23840313, 2013). "Thus, it is possible that KIF11 presents and additional therapeutic strategy for diabetes, although limiting exposure to the liver would be essential." (PMID 23840313, 2013).
liver disease (2 papers, 2023 to 2025). "Clinical analysis shows USP1 and KIF11 are overexpressed in HCC patients with portal hypertension and strongly correlate." (PMID 40546347, 2025). "Inhibition of USP1 with ML323 reduces KIF11 levels and suppresses tumor progression in vivo, identifying USP1 as a potential therapeutic target for HCC, particularly in patients with portal hypertension." (PMID 40546347, 2025).
lymph node metastases (2 papers, 2024 to 2025). "Upregulated KIF11 predicts poor prognosis and is positively related to lymph node metastasis and TNM stages." (PMID 38672404, 2024). "Several studies have identified KIF11/Eg5 as overexpressed at the RNA and protein levels in both NSCLC and SCLC compared to normal tissues, with high expression correlating with greater pathological stage, lymph node metastasis, and poor progression-free and overall survival rates." (PMID 40002279, 2025).
Obesity (2 papers, 2022 to 2024). Accumulation of substantial excess body fat. "The risk of obesity (BMI) is related to the NRBP1, KIF11, and KCNJ11 genes." (PMID 38915894, 2024).
psoriasis (2 papers, 2023 to 2025). An autoimmune condition characterized by red, well-delineated plaques with silvery scales that are usually on the extensor surfaces and scalp. "Additionally, KIF4A, KIF11, and KIF20A are linked to mitotic spindle formation and chromosome segregation, processes often disrupted in hyperproliferative conditions such as psoriasis and CD." (PMID 40406126, 2025).
retinal ciliopathy (2 papers, 2020 to 2021). "KIF11 has recently been shown to regulate primary cilia assembly dynamics and been implicated in human retinal ciliopathy." (PMID 34055805, 2021).
retinal degeneration (2 papers, 2022). Degeneration of the retina. "In a total of 35 subjects with KIF11 variants, chorioretinal dysplasia was found in 44.2% (31/70) of eyes and was the leading phenotype of KIF11-associated retinopathy, followed by retinal folds (34.3%, 24/70) and retinal degeneration (12.9%, 9/70)." (PMID 35456519, 2022). "The mutation of KIF11 is more likely to damage RPE and retinal photoreceptor cells and leads to chorioretinal dysplasia and retinal degeneration, which is in line with our findings." (PMID 35456519, 2022).
retinal detachment (2 papers, 2020 to 2022). An eye emergency condition which may lead to blindness if left untreated. "In fact, retinal detachment can be caused by many diseases; it is more meaningful to detect the difference in KIF11-associated retinopathy with FEVR in mild patients." (PMID 35456519, 2022).
anaplastic meningioma (1 paper, 2019). A WHO grade III meningioma characterized by the presence of malignant morphologic features, including malignant cytology and a very high mitotic index (20 or more mitoses per ten high power fields). "On a functional level, knockdown of kinesins in Ben-Men-1 cells and in the newly established anaplastic meningioma cell line NCH93 resulted in a significantly inhibited tumor cell proliferation upon siRNA-mediated downregulation of KIF11 in both cell lines by up to 95% and 71%, respectively." (PMID 30991738, 2019).
astrocytic tumor (1 paper, 2024). A glial tumor of the brain or spinal cord showing astrocytic differentiation. "Upregulated KIF11 is positively related to the WHO grade of astrocytoma, especially grading astrocytic tumors." (PMID 38672404, 2024).
benign prostatic hyperplasia (1 paper, 2024). A non-cancerous nodular enlargement of the prostate gland. "Additionally, Di-(2-ethylhexyl) phthalate has been shown to promote benign prostatic hyperplasia through the KIF11-Wnt/β-catenin signaling pathway." (PMID 39703506, 2024).
Blindness (1 paper, 2022). Blindness is the condition of lacking visual perception defined as a profound reduction in visual perception. "In line with their study, patients with KIF11 mutations showed variable clinical manifestations ranging from asymptomatic to blindness." (PMID 35456519, 2022).
bone metastasis (1 paper, 2025). Transfer of a neoplasm from its primary site to bones. "KIF11 has been identified as an independent predictor of bone metastasis in PCa patients and can guide clinical practice." (PMID 40956849, 2025).
Breast Invasive Carcinoma (1 paper, 2020). "The prognostic significance and performance of KIF11 were validated on 17 worldwide independent microarray datasets and two The Cancer Genome Atlas‐Breast Invasive Carcinoma sets." (PMID 32346924, 2020).
Chorioretinal atrophy (1 paper, 2025). Atrophy (wasting) of the choroid and retinal layers of the fundus. "However, KIF11-associated disease is also associated with chorioretinal atrophy—absent in our patients with DYRK1A-associated retinopathy—highlighting this as a potentially useful clinical marker to distinguish between the two." (PMID 40405340, 2025).
colon adenocarcinoma (1 paper, 2021). "Finally, the genes coexpressed with KIF11 or KIF14 in colon adenocarcinoma were identified and functionally annotated." (PMID 34575892, 2021).
dysplasia (1 paper, 2022). A usually neoplastic transformation of the cell, associated with altered architectural tissue patterns. "Choroidopathy was found to be the dominant ocular feature in KIF11-related retinopathy in cases with MCLMR, which is commonly described as focal choroidal atrophy or dysplasia with variable phenotypes ranging from mild RPE damage to diffuse choroidal dysplasia." (PMID 35456519, 2022).
endometrial cancer (1 paper, 2025). Primary or metastatic malignant neoplasm involving the endometrium (mucous membrane that lines the endometrial cavity). "Our findings in endometrial cancer, where high KIF11 expression combined with low KIF14 expression correlates with shorter overall survival, align with these studies." (PMID 40075652, 2025). "This study included the analysis of the expression of proteins KIF11 and KIF14 in endometrial cancer specimens and non-neoplastic endometrial tissues." (PMID 40075652, 2025).
endometrioid carcinoma (1 paper, 2025). "Our findings demonstrate a strong and consistent association between KIF11 and KIF14 expression and endometrioid carcinoma (EC), emphasizing their role in tumor progression." (PMID 40075652, 2025). "This study investigates the prognostic significance of KIF11 and KIF14 in endometrioid carcinoma, focusing on their potential as biomarkers and therapeutic targets." (PMID 40075652, 2025).
endometriosis (1 paper, 2025). The growth of functional endometrial tissue in anatomic sites outside the uterine body. "Our study has identified eight potential mitosis hub genes (KIF4A, BUB1B, NEK2, FBXO5, KIF11, CENPE, CCNA2, and NCAPG) that exhibit excellent diagnostic properties for endometriosis." (PMID 40772274, 2025). "Then, we identified 11 potential mitosis-related downregulated hub genes, among which eight genes (KIF4A, BUB1B, NEK2, FBXO5, KIF11, CENPE, CCNA2, and NCAPG) showed good diagnostic properties of endometriosis and two genes (CCNA2, CENPE) were closely related to infertile endometriosis." (PMID 40772274, 2025). "We used the GSE25628 dataset to detect the expression of selected target genes, and the results showed that the differential expression of eight MRHGs (KIF4A, BUB1B, NEK2, FBXO5, KIF11, CENPE, CCNA2, and NCAPG) between control and endometriosis patients was consistent with predictions." (PMID 40772274, 2025).
epilepsy (1 paper, 2021). A brain disorder characterized by episodes of abnormally increased neuronal discharge resulting in transient episodes of sensory or motor neurological dysfunction, or psychic dysfunction. "Furthermore, a novel heterozygous variant (c.733A>G, p.M245V) in the KIF11 gene was identified from the spouse with sensorineural hearing-loss and epilepsy." (PMID 34912366, 2021).
Ewing sarcoma (1 paper, 2023). A small round cell tumor that lacks morphologic, immunohistochemical, and electron microscopic evidence of neuroectodermal differentiation. "Furthermore, bioinformatic analysis of RNA expression data from solid cancers within DepMap portal indicated that KIF15 expression levels were the highest in Ewing sarcoma and that KIF11 expression levels were the second highest in Ewing sarcoma, only behind synovial sarcomas." (PMID 37894278, 2023). "Overall, we identified a novel combination of mitotic inhibitors targeting KIF11 and AURKA that is highly synergistic in inhibiting the growth of an aggressive tumor such as Ewing sarcoma." (PMID 37894278, 2023). "This study identified a synergistic combination of inhibitors for KIF11 (SB-743921) and AURKA that demonstrated significant pre-clinical activity in vitro and efficacy in an in vivo xenograft mouse model of Ewing sarcoma." (PMID 37894278, 2023).
fibrosis (1 paper, 2024). the formation of excess fibrous connective tissue in an organ or tissue in a reparative or reactive process. "To date, there have been limited reports on the relationships between CCNB2, NCAPG, KIF20A, KIF11, and BUB1B with SSc or fibrosis." (PMID 38343538, 2024).
hearing-loss (1 paper, 2021). "We found that the two reported hearing loss-associated variants (c.704C>G, p.[S235C] and c.730C>T, p.[H244Y]) and current variant (c.733A>G, p.[M245V]) in KIF11 are clustered in the second beta-sheet in the catalytic domain of Kinesin motor." (PMID 34912366, 2021). "Notably, genotype-phenotype analysis of KIF11-associated disorders revealed that the p.M245V and two reported hearing-loss-associated variants (p.S235C and p.H244Y) are all mapped to a single β-sheet (Ser235∼M245) in the kinesin motor domain." (PMID 34912366, 2021). "Our findings expand variant spectrums of hearing loss candidate genes, and shed new insights of pathogenetic effects of ATP6V1B2, TJP2, and KIF11 on hearing functions." (PMID 34912366, 2021). "Our findings expand the variant spectrum of hearing-loss-associated genes and provide new insights on understanding of hearing-loss candidate genes ATP6V1B2, TJP2, and KIF11." (PMID 34912366, 2021).
Infertility (1 paper, 2025). "The personalization of infertility care significantly improves with the incorporation of TUBB8, KIF11, and CKAP5 into the diagnostic framework of assisted reproduction." (PMID 40650169, 2025). "This thorough study presents new insights into the molecular mechanisms of infertility in women with unresolved oocyte arrest syndromes, highlighting the essential roles of TUBB8, KIF11, and CKAP5 in oocyte maturation and early embryonic development." (PMID 40650169, 2025). "The elucidation of molecular pathways involving TUBB8, KIF11, and CKAP5 has transformative potential in the diagnosis and treatment of infertility, particularly in cases with unresolved oocyte maturation arrest and early embryonic developmental failure." (PMID 40650169, 2025).
liposarcoma (1 paper, 2019). A usually painless malignant tumor that arises from adipose tissue. "YAP1 knockdown depleted FUS‐DDIT3‐expressing MLS 402‐91 and MLS 1765‐92 cells to a similar extent as knockdown of KIF11, an essential cell cycle regulator that served as positive control, whereas there was little effect in cell lines representing other liposarcoma subtypes." (PMID 30898787, 2019).
lymphangiectasia (1 paper, 2025). "Lymphoscintigraphy showed reduced tracer absorption, and intestinal lymphangiectasia was detected in one patient, pointing to impairment of lymphatic function caused by KIF11 haploinsufficiency." (PMID 41427784, 2025).
mental disorder (1 paper, 2024). A disease that has its basis in the disruption of mental process. "Neurodevelopmental disorders are commonly associated with KIF11 mutations, but no prior research has explored the connection between KIF11-associated disorder and mental disorders." (PMID 39359715, 2024).
metastasis (1 paper, 2024). The spread or migration of cancer cells from one part of the body (where they first appeared) to another. "Overexpression of KIF11 is positively related to tumor grade, TNM stages, and lymph node metastasis." (PMID 38672404, 2024).
metastatic disease (1 paper, 2024). "Overexpression of KIF11 is related to higher T stage, poor MFS, and bone metastasis occurrence; KIF11 mRNA is upregulated in stage ≥ T3 or metastatic disease compared with T2N0M0 disease; overexpressed nuclear KIF11 is observed in T4 tumors and metastatic disease." (PMID 38672404, 2024).
metastatic melanoma (1 paper, 2022). A melanoma that has spread from its primary site to another anatomic site. "Notably, the top 20 genes from topological analysis algorithms included four hub genes: CDK1, FOXM1, KIF11, and RFC4, which may involve in the development of metastatic melanoma." (PMID 35906389, 2022).
pediatric cancers (1 paper, 2025). "In pediatric cancers, KIF11 has been shown to be overexpressed and to have a prognostic role in Wilms tumors and in acute lymphocytic leukemia." (PMID 40281281, 2025).
pulmonary neuroendocrine tumors (1 paper, 2024). "Because high MKI67 expression is associated with shorter survival in patients with pulmonary neuroendocrine tumors, including SCLC, a high expression of KIF11 in SCLC would be compatible with its high malignancy." (PMID 39000337, 2024).
small cell carcinoma of the esophagus (1 paper, 2024). "However, high KIF11 expression levels have also been observed in small cell carcinoma of the esophagus." (PMID 39000337, 2024).
uterine cancer (1 paper, 2023). Primary or metastatic malignant neoplasm involving the uterine corpus and/or the cervix. "In female reproductive system tumors, KIF11 is a prognostic marker of uterine cancer and ovarian cancer." (PMID 37286702, 2023).